SIX3 (SIX homeobox 3)
Description:
Transcriptional regulator which can act as both a transcriptional repressor and activator by binding a ATTA homeodomain core recognition sequence on these target genes. During forebrain development represses WNT1 expression allowing zona limitans intrathalamica formation and thereby ensuring proper anterio-posterior patterning of the diencephalon and formation of the rostral diencephalon. Acts as a direct upstream activator of SHH expression in the rostral diencephalon ventral midline and that in turn SHH maintains its expression. In addition, Six3 activity is required for the formation of the telencephalon. During postnatal stages of brain development is necessary for ependymal cell maturation by promoting the maturation of radial glia into ependymal cells through regulation of neuroblast proliferation and migration. Acts on the proliferation and differentiation of neural progenitor cells through activating transcription of CCND1 and CCND2. During early lens formation plays a role in lens induction and specification by activating directly PAX6 in the presumptive lens ectoderm. In turn PAX6 activates SIX3 resulting in activation of PDGFRA and CCND1 promoting cell proliferation. Also is required for the neuroretina development by directly suppressing WNT8B expression in the anterior neural plate territory. Its action during retina development and lens morphogenesis is TLE5 and TLE4-dependent manner. Furthermore, during eye development regulates several genes expression. Before and during early lens development represses the CRYGF promoter by binding a SIX repressor element. Directly activates RHO transcription, or cooperates with CRX or NRL. Six3 also functions in the formation of the proximodistal axis of the optic cup, and promotes the formation of optic vesicles-like structures. During pituitary development, acts in parallel or alternatively with HESX1 to control cell proliferation through Wnt/beta-catenin pathway (By similarity). Plays a role in eye development by suppressing WNT1 expression and in dorsal-ventral patterning by repressing BMP signaling pathway.
Synonyms: HPE2
Tractability: PROTAC: ubiquitination databases record sites on it.
Gene: Protein-coding gene on chromosome 2 (44,941,702 to 44,946,071, forward strand). Ensembl gene ENSG00000138083.
Subcellular location: Nucleus
Subcellular location (Human Protein Atlas): Nucleoplasm
Gene Ontology:
Molecular function: protein binding; RNA polymerase II cis-regulatory region sequence-specific DNA binding; sequence-specific double-stranded DNA binding; transcription corepressor binding; DNA-binding transcription activator activity, RNA polymerase II-specific; DNA-binding transcription factor activity, RNA polymerase II-specific; DNA binding; histone deacetylase binding; sequence-specific DNA binding
Biological process: eye development; forebrain dorsal/ventral pattern formation; gene expression; negative regulation of DNA-templated transcription; apoptotic process involved in development; brain development; cell proliferation in forebrain; epithelial cell maturation; lens development in camera-type eye; lens fiber cell apoptotic process; lens fiber cell differentiation; negative regulation of neuron differentiation; neuroblast differentiation; neuroblast migration; optic vesicle morphogenesis; pituitary gland development; proximal/distal axis specification; regulation of cell cycle phase transition; regulation of cell population proliferation; regulation of neural precursor cell proliferation; regulation of neural retina development; regulation of neuroblast proliferation; regulation of transcription by RNA polymerase II; telencephalon development; telencephalon regionalization; and 2 more
Cellular component: chromatin; nucleus; transcription regulator complex
Genetic constraint (gnomAD): Loss-of-function variants: 2 observed, 16.27 expected, observed/expected ratio (o/e) 0.12, 90% interval 0.049 to 0.39. The upper end of that interval is the gene's LOEUF score, 0.39, which puts it in group 1 of 6, group 1 being the genes least tolerant of losing a copy. Missense variants: 347 observed, 437.31 expected, observed/expected ratio (o/e) 0.79, 90% interval 0.73 to 0.87. Synonymous variants: 243 observed, 199.06 expected, observed/expected ratio (o/e) 1.22, 90% interval 1.1 to 1.36.
Homologues: Orthologues: chimpanzee SIX3 (99% identical), pig SIX3 (98% identical), rat Six3 (98% identical), mouse Six3 (98% identical), macaque SIX3 (98% identical), dog SIX3 (96% identical), guinea pig SIX3 (89% identical), tropical clawed frog six3 (83% identical), zebrafish six3a (82% identical), zebrafish six3b (75% identical), Drosophila melanogaster Optix (57% identical), Caenorhabditis elegans ceh-32 (42% identical). Paralogues in human: SIX6 (61% identical), SIX4 (42% identical), SIX1 (40% identical), SIX2 (40% identical), SIX5 (38% identical), ANHX (20% identical).
Diseases named in the same sentence as SIX3 in open-access papers:
SIX3 is named in the same sentence as 57 diseases in open-access papers, as found by Europe PMC text mining. Sharing a sentence is not in itself a finding about the gene and the disease. The quoted sentences say what the papers report.
holoprosencephaly (21 papers, 2007 to 2025). Holoprosencephaly (HPE) is a complex brain malformation resulting from incomplete cleavage of the prosencephalon, occurring between the 18th and 28th day of gestation, and affecting both the forebrain and face, which results in neurological manifestations and facial anomalies of variable severity. "The direct regulation of Shh by Six3 has been observed in mice, and loss of Shh signalling in mice leads to defective midline patterning, including cyclopia, also found in humans with mutations in SIX3 and SHH." (PMID 31416264, 2019). "The functional importance of the C-terminal region was also implied from the mutational analysis of SIX3, a major causative gene in holoprosencephaly." (PMID 31844685, 2019). "Mutations in SIX3 can cause holoprosencephaly in humans, a condition associated with forebrain malformation, intellectual disability, ophthalmological abnormalities, and craniofacial features including cyclopia, nasal dysmorphology, and cleft lip/palate." (PMID 29423138, 2018). "Holoprosencephaly has also been associated with long-range regulator mutations leading to a haploinsufficiency of SIX3 or SHH proteins." (PMID 23284961, 2012). "During eye development, inactivation of Six3 causes cyclopia, small eyes or disrupted proximo-distal patterning of the OV in medaka embryos." (PMID 23145006, 2012). "Heterozygous mutations in SIX3 cause variable holoprosencephaly in humans and mice." (PMID 35951005, 2023). "However, only 25% of holoprosencephalic cases are due to mutations in known genes correlated with holoprosencephaly (e.g., Shh, Fgf8, Six3), leaving 75% of cases with unknown mutations." (PMID 33324176, 2020). "Loss of Six3 function produces essentially forebrain defects rostral to the prethalamus (diencephalon), with the absence of the telencephalon, hypothalamus, eyes, and pituitary gland, as well as the olfactory placodes, a phenotype similar to severe holoprosencephaly phenotypes in humans." (PMID 33324176, 2020). "Furthermore, FGF8 and SIX3 have been found to be mutated in holoprosencephaly (HPE), a common developmental defect in midline patterning of the forebrain and/or midface." (PMID 40401629, 2025). "Many of the altered genes, including BMP4, FGF8, SIX3 and LHX2, have previously been associated with PAE and phenotypes of FASD, like defects in heart and corpus callosum development as well as holoprosencephaly." (PMID 40401629, 2025). "In conclusion, Six3 or Shh null animals show a severe holoprosencephalic phenotype (with cyclopia), while diminishing variations in Shh and Six3 levels result in septo-optic dysplasia or holoprosencephaly, respectively, with different degrees of severity." (PMID 33324176, 2020). "In mice, the removal of one copy of Shh on its own does not cause malformations, but the loss can cause semilobar holoprosencephaly if one copy of Six3 is also deleted." (PMID 34576017, 2021). "Indeed, mutations in signaling molecules (e.g., SHH and FGFs) and transcription factors (e.g., SIX3, SOX2, and SOX3) have been implicated in midline forebrain defects such as septo-optic dysplasia and holoprosencephaly." (PMID 33324176, 2020). "Eya4 and Six3 have been demonstrated to interact in a study of holoprosencephaly, indicating that Eya4 may be the functional bridge between Six3 and Six3OS in the developing ventral forebrain." (PMID 21936910, 2011). "Third, while some progress has been made in understanding holoprosencephaly (HPE)—particularly through the identification of variants in genes such as SHH, SIX3, ZIC2, and TGIF1—most of these findings originate from non-Latin American cohorts." (PMID 40700109, 2025). "It has been reported that molecular evaluation of foetuses with holoprosencephaly showed high incidence of microdeletions in four HPE genes, one of which was SIX3 gene." (PMID 26064910, 2015).
holoprosencephaly (continued). "Consistent with this expression, Six3-null mice die at birth, lacking most of the head structures anterior to the midbrain, including eyes, and mutations in SIX3 have been found in humans affected by holoprosencephaly and aprosencephaly/atelencephaly." (PMID 17617896, 2007). "Other gene mutations that relates to holoprosencephaly, including ZIC2, SIX3, TGIF1, CDON, FGFR1, CENPF and DHCR7, were not identified." (PMID 39859210, 2025). "Rare cases (about 5%) of severe SLO partients exhibit holoprosencephaly-like features without mutations in the main holoprosencephaly genes SHH, ZIC2, SIX3 and TGIF." (PMID 34576017, 2021). "They found that the usual mutations associated with human holoprosencephaly (SHH, TGIF, ZIC2 and SIX3) and GLI 3 were not present, and cholesterol studies were normal." (PMID 34576017, 2021). "The lack of SIX3/SIX6 genes and/or their improper regulations lead to death, inborn defects, or abnormalities (e.g., holoprosencephaly), and cancers." (PMID 31844685, 2019).
breast carcinoma (9 papers, 2015 to 2023). "Higher levels of SIX3 were associated with decreased tumor proliferation and metastasis, leading to better survival outcomes and/or prognosis in breast cancer, astrocytoma, glioblastoma, and lung adenocarcinoma." (PMID 34490256, 2021). "As a negative regulator of the Wnt pathway, SIX3 inhibited breast cancer carcinogenesis and metastasis by recruiting the LSD1/NuRD (MTA3) complex." (PMID 36750914, 2023). "In breast cancer, Six3 was transcriptionally targeted for repression by metastatic tumor antigen 1 (MTA1) which in turn upregulated Wnt1." (PMID 34490256, 2021). "Consistent with previous findings in breast cancer cells, we observed an enrichment of Six3 to the promoter regions of Wnt1 compared to the corresponding IgG control in AGS and HGC-27 cells." (PMID 34545072, 2021). "Of note, the Wnt/β-catenin signaling pathway is involved in Six3 function in glioma and breast cancer development." (PMID 34545072, 2021). "As a negative regulator of Wnt pathway, SIX3 inhibited breast cancer carcinogenesis and metastasis through recruiting the LSD1/NuRD complex." (PMID 32550045, 2020). "Increased SIX1–3 expression is linked to high histological grade and ER status, and that SIX2 and SIX3 are upregulated in basal-like breast cancer." (PMID 27399099, 2016). "Repression of Wnt1 by Six3 has been detected in mammary glands as well as breast cancer cells." (PMID 34490256, 2021). "On the contrary, high SIX3 level was found to be associated with better OS (HR: 0.44, 95% CI: 0.20–0.96; P = 0.593 and I2 = 0.0%) and RFS (HR: 0.49, 95% CI: 0.32–0.76; P = 0.451 and I2 = 0.0%) of basal-like breast cancer patients." (PMID 27399099, 2016). "SIX1 and SIX6 could serve as an unfavorable factor for prognosis of luminal breast cancer patients, while SIX3 is capable of playing a protective role in prognosis of basal-like breast cancer patients." (PMID 27399099, 2016). "There is no significant publication bias for the following analysis: mRNA expression of SIX family members: breast cancer risk: SIX1: Begg test P = 0.707, Egger test P = 0.568; SIX3: Begg test P = 0.734, Egger test P = 0.474; SIX4: Begg test P = 0.707, Egger test P = 0.381." (PMID 27399099, 2016). "In consistent with this experimental study, expression profile analysis indicated that high SIX3 mRNA level was a protective factor for OS and RFS of basal-like breast cancer patients." (PMID 32550045, 2020). "Moreover, expression profile analysis indicated that high SIX3 mRNA level was a protective factor for OS and RFS of basal-like breast cancer patients." (PMID 36750914, 2023). "Sineoculis homeobox homolog (SIX) family proteins, including SIX1, SIX2, SIX3, SIX4, SIX5, and SIX6, have been implicated in the initiation and progression of breast cancer, but the role of each member in breast tumor is not fully understood." (PMID 27399099, 2016). "However, high SIX3 mRNA level was a protective factor for OS and RFS of basal-like breast cancer patients." (PMID 27399099, 2016). "Although the protective role of SIX3 in the clinical outcome of basal-like breast cancer has not been reported, this role in lung adenocarcinoma has been identified." (PMID 27399099, 2016). "Moreover, SIX genes are deregulated in several types of malignancies, including breast cancer and hepatocellular carcinoma (SIX1), lung cancer (SIX2), chondrosarcoma (SIX3), and acute T-cell leukemia (SIX6)." (PMID 26473286, 2015). "Besides, researchers found that expression of Six3 is negatively correlated with breast cancer malignancy and further studies on the mechanism revealed that Six3 recruits LSD1/NuRD(MTA3) complex to Wnt1 promoters, thus resulting in a reduction of Wnt1 expression levels in breast cancer." (PMID 34545072, 2021).
lung carcinoma (9 papers, 2013 to 2022). "SIX3 expression is associated with improved survival in lung cancer, whereas TRIM27 expression indicates a poor survival outcome based on a Kaplan-Meier Plotter database and our hospital cohort." (PMID 33264103, 2020). "A previous study also found that SIX3 expression is associated with tumor size, gender, survival, and recurrence in lung cancer, suggesting that SIX3 may be an informative prognostic marker for lung cancer." (PMID 33264103, 2020). "As a DNA-binding transcription factor Six3 is downregulated in lung cancer and correlated with tumor size, OS, and recurrence of patients with lung adenocarcinoma." (PMID 34545072, 2021). "A previous study suggested that SIX3 inhibits the mRNA expression of metastasis- and proliferation-related genes through suppressing the activation of Wnt/β-catenin in lung cancer." (PMID 33264103, 2020). "Restoration of SIX3 expression in lung cancer cells with low endogenous SIX3 resulted in suppressed cell proliferation and migration." (PMID 30980423, 2019). "Downregulation of SIX3 due to the methylation of the SIX3 promoter is observed in lung adenocarcinoma tissues and lung cancer cell lines, where mRNA expression of the gene is also associated with higher survival rate." (PMID 30545422, 2018). "In this study we intend to investigate the expression and function of SIX3 in human lung cancer, and potential of SIX3 expression as a prognostic biomarker for patients with lung adenocarcinoma." (PMID 23977152, 2013). "Wound healing assays were used to assess cell migration, and microarrays were utilized to examine genes regulated by SIX3 in lung cancer cells." (PMID 23977152, 2013). "As ubiquitination is associated with many biological processes, such as cell differentiation, proliferation, apoptosis, cell cycle, DNA repair, and inflammation, SIX3, a tumor suppressor in lung cancer, was bioinformatically predicted as a substrate for several human E3 ubiquitin ligases." (PMID 33264103, 2020). "A recent study reported that the DNA-binding transcriptional factor SIX3 is essential during embryonic development in vertebrates and capable of downregulating target genes of the Wnt/β-catenin pathway in lung cancer, indicating negative regulation of Wnt/β-catenin activation." (PMID 33264103, 2020). "However, SIX3 is downregulated in lung cancer tissues compared with adjacent normal lung tissues measured by IHC analysis, which is in line with our results." (PMID 33264103, 2020). "We measured the expression of TRIM27 and SIX3 as well as investigated whether there was a correlation between them in lung cancer tissue samples." (PMID 33264103, 2020). "Previous studies have shown that SIX3 acts as a suppressor in lung cancer by modulating proliferation and migration-related genes, such as S100P and TGFB3, and the Wnt/β-catenin signaling pathway is involved in SIX3 function in glioma development and vertebrate forebrain development." (PMID 33264103, 2020). "Although these findings indicate that SIX3 may regulate tumorigenesis of lung cancer via Wnt/β-catenin signaling, the regulation of this SIX3-Wnt/β-catenin signaling axis remains largely unknown." (PMID 33264103, 2020). "Importantly, SIX3 inhibited TRIM27-induced NSCLC cell proliferation and metastasis indicating the involvement of SIX3 in TRIM27-mediated tumorigenesis of lung cancer." (PMID 33264103, 2020). "Furthermore, we found that TRIM27 and SIX3 expression in lung cancer tissues is negatively correlated." (PMID 33264103, 2020). "However, the prognostic import of either TRIM27 or SIX3 for lung cancer of different tumor stage or histology requires further investigation." (PMID 33264103, 2020). "Moreover, SIX3 was downregulated in cells from lung cancer cell lines and inhibited NSCLC cell proliferation and metastasis, findings which are consistent with those of previous studies." (PMID 33264103, 2020). "SIX3 was also methylation-silenced in lung cancer cell lines." (PMID 23977152, 2013).
lung carcinoma (continued). "In addition, TRIM27 and SIX3 expression in lung cancer tissues is negatively correlated." (PMID 33264103, 2020). "Similarly, the amount of protein of SMURF2 and TRIM27 was also increased and that of SIX3 was decreased in lung cancer tissues compared with adjacent normal lung tissues, although we found that there was a significant correlation between the protein level of SIX3 and TRIM27, but not of SMURF2." (PMID 33264103, 2020). "SIX3 may play an important role as a novel suppressor in human lung cancer." (PMID 23977152, 2013). "This evidence strongly support our hypothesis and clarifies a relationship between SIX3 and TRIM27 in the pathogenesis of lung cancer." (PMID 33264103, 2020). "Restoration of SIX3 in lung cancer cells lacking endogenous SIX3 suppressed cell proliferation and migration, and downregulated a number of genes involved in proliferation and metastasis such as S100P, TGFB3, GINS3 and BAG1." (PMID 23977152, 2013). "Previous studies have provided evidence that SIX3 mRNA expression is upregulated in NSCLC and lung adenocarcinoma tissues compared with that of normal lung tissue, a finding which is inconsistent with our decreased SIX3 protein levels in lung cancer tissues measured by IHC and western blotting." (PMID 33264103, 2020). "In addition, we found that TRIM27 is upregulated in lung cancer tissues compared with normal lung tissues in our cohort, which is consistent with that found in a previous study, and that higher TRIM27 expression correlates with lower SIX3 expression in lung cancer tissue samples from our cohort." (PMID 33264103, 2020). "SIX3, unlike other members of the SIX family, is a suppressor in proliferation and migration of lung cancer cells." (PMID 27821176, 2016). "However, the exact mechanism how SIX3 and TRIM27 regulate S100P in lung cancer is not known, and thus, warrants further investigation." (PMID 33264103, 2020).